RP2 (RP2 activator of ARL3 GTPase)
Description:
Acts as a GTPase-activating protein (GAP) involved in trafficking between the Golgi and the ciliary membrane. Involved in localization of proteins, such as NPHP3, to the cilium membrane by inducing hydrolysis of GTP ARL3, leading to the release of UNC119 (or UNC119B). Acts as a GTPase-activating protein (GAP) for tubulin in concert with tubulin-specific chaperone C, but does not enhance tubulin heterodimerization. Acts as a guanine nucleotide dissociation inhibitor towards ADP-ribosylation factor-like proteins.
Synonyms: TBCCD2; NME10; NM23-H10; DELXp11.3; XRP2
Tractability: Small molecule: a structure with a bound ligand is known. Antibody: UniProt places it where antibodies can reach, with high confidence; its Gene Ontology location is reachable by antibodies, with high confidence. PROTAC: ubiquitination databases record sites on it; its protein half-life has been measured.
Gene: Protein-coding gene on chromosome X (46,836,928 to 46,889,240, forward strand). Ensembl gene ENSG00000102218.
Subcellular location: Cell membrane; Cell projection, cilium
Subcellular location (Human Protein Atlas): End piece; Mid piece; Plasma membrane; Principal piece; Acrosome; Cytosol; Nuclear bodies; Nucleoplasm; Vesicles
Pathways (Reactome):
Organelle biogenesis and maintenance: Trafficking of myristoylated proteins to the cilium
Gene Ontology:
Molecular function: GTPase activator activity; magnesium ion binding; protein binding
Biological process: post-chaperonin tubulin folding pathway; post-Golgi vesicle-mediated transport; cilium assembly; protein folding; visual perception
Cellular component: ciliary basal body; cytoplasm; cytoplasmic vesicle; extracellular exosome; plasma membrane; cilium; periciliary membrane compartment; centriole; Golgi apparatus
Gene-disease validity (ClinGen):
ClinGen rates the evidence that RP2 causes each of these diseases.
RP2-related retinopathy (X-linked): Definitive. A retinopathy caused by variants in the X-linked gene, RP2.
Homologues: Orthologues: chimpanzee RP2 (99% identical), macaque RP2 (99% identical), rabbit RP2 (95% identical), pig RP2 (92% identical), guinea pig RP2 (90% identical), dog RP2 (89% identical), rat Rp2 (89% identical), mouse Rp2 (88% identical), tropical clawed frog rp2 (73% identical), zebrafish rp2 (70% identical), Caenorhabditis elegans rpi-2 (29% identical).
Diseases named in the same sentence as RP2 in open-access papers:
RP2 is named in the same sentence as 53 diseases in open-access papers, as found by Europe PMC text mining. Sharing a sentence is not in itself a finding about the gene and the disease. The quoted sentences say what the papers report.
retinitis pigmentosa (11 papers, 2014 to 2024). Retinitis pigmentosa (RP) is an inherited retinal dystrophy leading to progressive loss of the photoreceptors and retinal pigment epithelium and resulting in blindness usually after several decades. "The RP2 protein (also known as NME10) is encoded by a gene that when mutated causes retinitis pigmentosa in humans." (PMID 30111592, 2018). "Variants in RP2 (retinitis pigmentosa 2) which encodes RP2 are associated with X-linked retinitis pigmentosa type 2 [MIM: 312600]." (PMID 26964041, 2016). "The mutation of Retinitis Pigmentosa 2 (RP2) can cause retinitis pigmentosa, it is a prognostic factor of osteosarcoma, however, its role in glioma remains unclear." (PMID 37602882, 2023). "Similarly, mutations in RP2 cause retinitis pigmentosa accompanied by eoHM in humans, but knockdown of rp2 in zebrafish resulted in small eye size." (PMID 30689892, 2019). "Biochemical studies on the human RP2 protein, XRP2 (which is mutated in a subset of retinitis pigmentosa patients), suggests that XRP2 and canonical TBCC have a partial functional overlap." (PMID 24257747, 2014). "The rp2, cerkl, myo7aa, ush1c, and pcdh15a genes are related to retinitis pigmentosa." (PMID 38789412, 2024). "Our proteomic data showed significant changes in the levels of proteins for retinitis pigmentosa (RPE65, RP2, MERTK, and RBP3), X-linked retinoschisis (RS1), CRB1-retinal dystrophy (CRB1), Usher syndrome (PCDH15), and Leber congenital amaurosis (RD3 and KCNJ13)." (PMID 36139394, 2022). "By checking the background information, we found that ARL3 can directly bind to RP2, and RP2 can act as the GTP-enzyme activating protein of ARL3, thus affecting intracellular microtubule regulation and protein transport, which can cause diseases such as retinitis pigmentosa." (PMID 37602882, 2023).
retinal degeneration (10 papers, 2011 to 2025). Degeneration of the retina. "Understanding the detailed molecular mechanisms by which RP2 mutations lead to retinal degeneration is essential for the development of effective therapeutic strategies." (PMID 39941570, 2025). "The Arl3 GAP RP2, on the other hand, causes non-syndromic retinal degeneration, providing more evidence that the impact of excess active Arl3 on cells is more detrimental for retinal photoreceptors than other ciliated cells throughout the body." (PMID 36598133, 2023). "Mutations in the retinitis pigmentosa 2 (RP2) gene are associated with X-linked RP, which is a phenotypically heterogenic form of retinal degeneration." (PMID 21738648, 2011). "As RP2 mutations cause retinal degeneration in patients, we utilized retinal degeneration phenotype as a read out for the effect of silencing of the rp2 gene in zebrafish." (PMID 21738648, 2011). "Mutations in the RP2 gene can result in various degrees of retinal degeneration, but there remains a lack of clear genotype–phenotype correlations." (PMID 39941570, 2025). "The underlying mechanism of RP2-associated retinal degeneration in humans remains poorly understood, and existing animal models of RP2-linked XLRP do not fully replicate the severe phenotype observed in patients." (PMID 39941570, 2025). "RP2 represents a gene causing another form of XL RP (RP2, OMIM #300757y: X-linked) that affects males with early-onset severe retinal degeneration, early macular involvement, and consequently severe visual function loss due to the loss of foveal photoreceptors." (PMID 38610844, 2024). "The mechanism of RP2-associated retinal degeneration in humans is unclear, and animal models of RP2 XLRP do not recapitulate this severe phenotype." (PMID 32531192, 2020). "Collectively, our findings suggest that RP2 and Arl3 regulate the trafficking of specific kinesins to cilia tips and provide additional evidence that TRIDs could be clinically beneficial for patients with this retinal degeneration." (PMID 28444310, 2017). "Some other retina degeneration animal models such as CC2D2A, RP2, and EYS are characterized by opsin mislocalization and further photoreceptor cell loss, and these genes are associated with cilia transport." (PMID 37351277, 2023).
myopia (9 papers, 2015 to 2025). "Myopia is also frequently associated with pathogenic variants in the ARL3 GAP RP2, which cause X-linked IRD." (PMID 40037334, 2025). "Therefore, in clinical practice, patients with X-linked inheritance, high myopia, early onset of central visual acuity impairment, and complicated with early-onset macular atrophy should first be considered for RP2 gene variants and prioritized for screening of related gene variants." (PMID 37749571, 2023). "It has been found as studied that approximately 50% of RP2 gene-related RP patients are accompanied by high myopia." (PMID 37749571, 2023). "The hypothesis posed by our study can be generalized to other early-onset, cone-dominated dystrophies associated with myopia, such as CDHR1 and RP2 retinal dystrophies." (PMID 40535564, 2025). "RP2 and CNGB3 are expressed in cones and rods and are associated with syndromic myopia." (PMID 36418970, 2022). "Also, although myopia has been associated with xlRP caused by mutations in both RPGR and RP2, it is not exclusively found in this phenotype, and therefore was not used as a diagnostic criterion of xlRP." (PMID 26197217, 2015). "In view of this, in young patients with high myopia and ERG anomalies, CACNAF1, RPGR, and RP2 genotypes should be excluded even in the absence of night blindness." (PMID 39596324, 2024).
Retinal dystrophy (8 papers, 2019 to 2026). Retinal dystrophy is an abnormality of the retina associated with a hereditary process. "Leber congenital amaurosis (LCA) caused by RPGR or RP2 mutation, which is one of the most severe forms of inherited retinal dystrophy, was reported in a Chinese cohort." (PMID 30917587, 2019). "Among cases of high myopia with ocular involvement (38.9%), a genetic cause was found in 8 out of 14 probands, including (likely) pathogenic variants in genes related to retinal dystrophies (CACNA1F, RPGR, RP2, NDP)." (PMID 39495751, 2024). "In the group with only ocular involvement, we observed 6 cases of (probably) pathogenic variants in genes associated with retinal dystrophies (RPGR; N = 2, CACNA1F; N = 2, RP2, NDP), which corresponds to 27.3% of all genetically confirmed cases of HM." (PMID 39495751, 2024). "Specifically, HM was identified in six children with retinal dystrophies (RPGR; N = 2, CACNA1F; N = 2, RP2, NDP) and one child each of corneal dystrophy (ZEB1) and Stickler syndrome (causative variant in the COL9A2 gene)." (PMID 39495751, 2024). "Some of these proteins are well-studied in retinal dystrophy, such as CRB1, RP2, RPE65, and PCDH15." (PMID 36139394, 2022). "Using Oxford Nanopore Technology sequencing, we analysed 194 patients with retinal dystrophy (RD) (142 men and 52 women) suspected to be either X-linked (n = 42) or autosomal (n = 152), and for whom first-line sequencing of 230 retinal dystrophy genes, including RP2 and RPGRex1-19, was negative." (PMID 41686256, 2026).
choroideremia (5 papers, 2011 to 2021). Choroideremia (CHM) is an X-linked chorioretinal dystrophy characterized by progressive degeneration of the choroid, retinal pigment epithelium (RPE) and retina. "Although it is widely assumed that the rod photoreceptors are the site of primary pathology, the effect of RP2 loss on cone photoreceptor and RPE function cannot be disregarded, especially given the prevalence of macular atrophy and choroideremia-like symptoms associated with loss of RP2 function." (PMID 25292197, 2015).
ciliopathies (3 papers, 2015 to 2020). "Reverse genetic mutations in the CC/TZ protein CC2D2A, axoneme protein RP2, and myosin 7A result in photoreceptor degeneration in zebrafish, indicating that zebrafish are an excellent model for the study of photoreceptor diseases associated with ciliopathies." (PMID 27737822, 2016).
glioma (3 papers, 2022 to 2024). A benign or malignant brain and spinal cord tumor that arises from glial cells (astrocytes, oligodendrocytes, ependymal cells). "In conclusion, our data suggested that a worse prognosis for glioma patients is frequently linked to increased RP2 expression." (PMID 37602882, 2023). "As a result, we found RP2 was positively associated with the infiltration of Neutrophils, CD4+T cells, B cells, Dendritic cells, and Macrophages in glioma." (PMID 37602882, 2023). "This study’s significance and uniqueness stem from the discovery of RP2 as a new, glioma-independent predictive factor that is intimately connected to cell proliferation and immune infiltration." (PMID 37602882, 2023). "In our study, RP2 expression was upregulated in glioma and the RP2 promoter was hypomethylated in glioma." (PMID 37602882, 2023). "We searched the expression level of candidate genes by GEPIA and found that only five genes (F11R, YBX1, BCAT1, IMPAD1, and RP2) were significantly upregulated in gliomas." (PMID 35402226, 2022). "Besides, our corresponding experimental results also demonstrated that overexpression of RP2 contributes to cell proliferation in glioma." (PMID 37602882, 2023). "Although we were aware that RP2 was expressed significantly more frequently in gliomas and that this may result in a bad prognosis, we didn’t know what was causing it." (PMID 37602882, 2023). "The results showed that RP2 was highly expressed in glioma, and its overexpression could lead to poor prognosis." (PMID 37602882, 2023). "Therefore, we speculated that overexpression of RP2 may also affect the progression of glioma through the interaction with ARL3." (PMID 37602882, 2023). "Furthermore, we investigated the correlation between the expression of RP2 and LAPTM4A and the clinicopathological features of glioma patients using the CGGA database." (PMID 38613802, 2024). "Notably, of these rigorously selected genes, RP2 and LAPTM4A demonstrated not only independent prognostic values for glioma patients but also displayed high Area Under ROC Curve (AUC) values." (PMID 38613802, 2024). "The findings demonstrated a favorable correlation between the expression of most cell checkpoints and the expression of RP2 in GBMLGG, demonstrating that RP2 overexpression might disturb the normal cell cycle and promote the proliferation of glioma." (PMID 37602882, 2023). "Based on the data from TCGA and GTEx, we identified RP2 as the most related gene for glioma by WGCNA, and used a series of bioinformatics analyses including LinkedOmics, GSCA, CTD, and so on, to explore the expression of RP2 in glioma and the biological functions it is involved in." (PMID 37602882, 2023). "The expression of RP2 in GBMLGG was positively related with TMB, suggesting that high expression of RP2 may promote the development of cancer by affecting gene mutations in glioma, meanwhile, a low mutation rate is not conducive to immunotherapy." (PMID 37602882, 2023).
cone-rod dystrophy (2 papers, 2022 to 2024). Inherited retinal dystrophies that belong to the group of pigmentary retinopathies. "While the phenotype of the rp2 mutant follows a progressive rod-cone dystrophy consistent with RP, it is worth noting that the rate of degeneration is quite slow compared to humans with RP2 mutations." (PMID 35693295, 2022). "The other IRD group included Stargardt's disease carrying ABCA4 variants, as well as individuals with Cone-Rod Dystrophy (CORD) or RP presenting with various genetic variants such as RDH12, RPGR, LCA5,CEP290, RP2, USH2A, and EYS." (PMID 38466290, 2024).
night blindness (2 papers, 2021 to 2024). Inability to see clearly in dim light. "This was in clear contrast to those with RPGR and RP2 variants, with 81% who were myopic and suffered from more severe night blindness in the juvenile cohort." (PMID 39596324, 2024). "Two families (families 43 and 44) had a family history of RP and night blindness caused by different mutations of RP2, which included the reported splicing mutation c.769-2A > G and the novel frameshift mutation c.572_582dup11." (PMID 33781268, 2021).
retinal disease (2 papers, 2020). "This study provides insights into the use of ROs for retinal disease modeling, with a phenotype related to loss of RP2 that is unique to the human retina cell culture model." (PMID 32531192, 2020). "Here, we developed gene-edited isogenic RP2 knockout (RP2 KO) induced pluripotent stem cells (iPSCs) and RP2 patient-derived iPSC to produce 3D retinal organoids as a human retinal disease model." (PMID 32531192, 2020). "For example, the Rp2–/– mouse model poorly replicates human retinal disease caused by absence of RP2 function." (PMID 33262683, 2020).
acute myeloid leukaemia (1 paper, 2013). "We also showed that RP2 inhibitors induce apoptosis in proliferating and dormancy-enriched KG1a cells and in the CD71neg CD34pos subset of primary acute myeloid leukaemia cells." (PMID 23767415, 2013).
autoimmune disease (1 paper, 2023). A disorder resulting from loss of function or tissue destruction of an organ or multiple organs, arising from humoral or cellular immune responses of the individual to their own tissue constituents. "KEGG enrichment analysis also showed that RP2 is enriched in pathways related to cell cycle, DNA replication, antigen processing and presentation, and the occurrence and development of many autoimmune diseases and various types of inflammation." (PMID 37602882, 2023).
autosomal dominant retinitis pigmentosa (1 paper, 2016). Autosomal dominant retinitis pigmentosa (RP) is an autosomally dominant inherited retinal dystrophy leading to progressive loss of the photoreceptors and retinal pigment epithelium and resulting in blindness usually after several decades. "The other two remained with the diagnosis of RP but turned out to be an X-linked (xlRP) and autosomal dominant retinitis pigmentosa (adRP) with mutations in RP2 (RP-1201) and RP1 (RP-1772) respectively." (PMID 26806561, 2016).
cryptosporidiosis (1 paper, 2022). Intestinal infection with organisms of the genus Cryptosporidium. "The present study reports the recombinant production of rP2 and rP23 antigens of C. parvum as antigens for detecting human cryptosporidiosis using indirect ELISA tests." (PMID 36369769, 2022). "Our results showed that combination of rP23 and rP2 antigens in ELISA significantly increases the performance of C. parvum serodiagnosis in human cryptosporidiosis." (PMID 36369769, 2022). "Furthermore, due to antigenic properties of rP2/rP23 antigen, it can be used for the diagnosis of human cryptosporidiosis." (PMID 36369769, 2022).
glioblastoma (1 paper, 2023). The most malignant astrocytic tumor (WHO grade IV). "Futhermore, we discovered that the mRNA expression of RP2 was most pronounced in glioblastoma among all histological types." (PMID 37602882, 2023).
Leigh syndrome (1 paper, 2022). A progressive neurological disease defined by specific neuropathological features associating brainstem and basal ganglia lesions. "In this study, we present a novel zebrafish model for Leigh Syndrome, French Canadian Type (LSFC) identified through the RP2 gene-breaking transposon insertional mutagenesis screen." (PMID 36408801, 2022).
leukaemia (1 paper, 2013). "We suggest that RP2 inhibitors may be a useful class of agent for targeting dormant leukaemia cells." (PMID 23767415, 2013).
lung carcinoma (1 paper, 2025). "Five of the eight NSCLC/lung cancers harboring a RASGRF fusion were adenocarcinomas (corresponding to the NSCLCs containing PACSIN2-RASGRF1, DLG1-RASGRF1, RP2-RASGRF1, NPTN-RASGRF1, and OCLN–RASGRF2)." (PMID 40615519, 2025).
microphthalmia (1 paper, 2011). Congenital or developmental anomaly in which the eyeballs are abnormally small. "Morpholino-mediated depletion of rp2 in zebrafish resulted in perturbations in photoreceptor development and microphthalmia (small eye)." (PMID 21738648, 2011). "Our analysis revealed that suppression of rp2 in zebrafish results in microphthalmia (small eye) (∼15% of defective embryos) and abnormal photoreceptor development in a majority (∼90%) of embryos, although retinal development seemed to proceed normally, at least up to 5 dpf." (PMID 21738648, 2011). "Notably, the tested RP2 mutants exhibited variable degrees of rescue of rod versus cone photoreceptor development as well as microphthalmia." (PMID 21738648, 2011). "While RP2 R118H and RP2 E138G resulted in eye diameter that was comparable to that with WT RP2, other mutants did not seem to achieve a rescue of the microphthalmia in defective embryos." (PMID 21738648, 2011).
Pearson syndrome (1 paper, 2024). Pearson syndrome is characterized by refractory sideroblastic anemia, vacuolization of bone marrow precursors and exocrine pancreatic dysfunction. "Remarkably, half of them (n = 4/8) were genotypically attributed to syndromic IRDs (syndromic: COH1, USH2A, RNU4ATAC; Pearson syndrome; isolated: RPGR, RP2, CACNA1F)." (PMID 39596324, 2024).